ENSG00000206592
Synonyms: LOC124900205
Gene: Small nucleolar RNA gene on chromosome 5 (79,220,942 to 79,221,073, forward strand). Ensembl gene ENSG00000206592.
Gene Ontology:
Biological process: RNA processing
Cellular component: nucleolus
Homologues: Paralogues in human: SNORA18 (89% identical).